CRIPTO (cripto, EGF-CFC family member)
Description:
GPI-anchored cell membrane protein involved in Nodal signaling. Cell-associated CRIPTO acts as a Nodal coreceptor in cis. Shedding of CRIPTO by TMEM8A modulates Nodal signaling by allowing soluble CRIPTO to act as a Nodal coreceptor on other cells. Could play a role in the determination of the epiblastic cells that subsequently give rise to the mesoderm.
Synonyms: CRGF; CRIPTO-1; TDGF1; CR; CR-1
Tractability: Antibody: UniProt places it where antibodies can reach, with high confidence; its Gene Ontology location is reachable by antibodies, with high confidence; UniProt predicts a signal peptide or a membrane-spanning region. Other modalities: a drug acting on it is in phase 1 trials.
Safety:
Unwanted effects reported when the protein is acted on. In parentheses: how it was acted on, where the effect was seen, and who reports it.
Decrease, Population growth rate (activation; source: AOP-Wiki)
Gene: Protein-coding gene on chromosome 3 (46,573,633 to 46,584,684, forward strand). Ensembl gene ENSG00000241186.
Subcellular location: Cell membrane; Secreted
Subcellular location (Human Protein Atlas): Vesicles; Predicted to be secreted
Pathways (Reactome):
Developmental Biology: POU5F1 (OCT4), SOX2, NANOG activate genes related to proliferation; Regulation of signaling by NODAL; Signaling by NODAL
Gene Ontology:
Molecular function: growth factor activity; protein binding; signaling receptor binding; activin receptor binding; nodal binding
Biological process: cell migration involved in sprouting angiogenesis; cellular response to epidermal growth factor stimulus; cellular response to fibroblast growth factor stimulus; cellular response to hepatocyte growth factor stimulus; cellular response to interleukin-6; cellular response to tumor necrosis factor; cellular response to type II interferon; epidermal growth factor receptor signaling pathway; heart development; negative regulation of apoptotic process; positive regulation of cell migration; positive regulation of cell population proliferation; positive regulation of endothelial cell migration; positive regulation of MAP kinase activity; positive regulation of MAPK cascade; regulation of signal transduction; anterior/posterior axis specification, embryo; anterior/posterior pattern specification; blood vessel development; cell differentiation; determination of left/right symmetry; embryo development ending in birth or egg hatching; mammary gland development; morphogenesis of a branching structure; nodal signaling pathway; and 1 more
Cellular component: apical plasma membrane; cell surface; extracellular region; membrane raft; plasma membrane
Genetic constraint (gnomAD): Loss-of-function variants: 20 observed, 21.87 expected, observed/expected ratio (o/e) 0.91, 90% interval 0.64 to 1.33. The upper end of that interval is the gene's LOEUF score, 1.33, which puts it in group 5 of 6, group 1 being the genes least tolerant of losing a copy. Missense variants: 225 observed, 255.61 expected, observed/expected ratio (o/e) 0.88, 90% interval 0.79 to 0.98. Synonymous variants: 69 observed, 88.19 expected, observed/expected ratio (o/e) 0.78, 90% interval 0.64 to 0.96.
Gene-disease validity (ClinGen):
ClinGen rates the evidence that CRIPTO causes each of these diseases.
congenital heart disease (autosomal dominant): Limited. A heart disease that is present at birth.
Homologues: Orthologues: chimpanzee CRIPTO (98% identical), macaque TDGF1 (91% identical), rat Cripto (64% identical), mouse Cripto (63% identical). Paralogues in human: CRIPTO3 (97% identical), CFC1 (27% identical), CFC1B (26% identical), EGFL7 (23% identical), EGFL8 (19% identical).
Diseases named in the same sentence as CRIPTO in open-access papers:
CRIPTO is named in the same sentence as 45 diseases in open-access papers, as found by Europe PMC text mining. Sharing a sentence is not in itself a finding about the gene and the disease. The quoted sentences say what the papers report.
non-small cell lung carcinoma (6 papers, 2020 to 2023). A group of at least three distinct histological types of lung cancer, including non-small cell squamous cell carcinoma, adenocarcinoma, and large cell carcinoma. "In lung cancer, serum levels of soluble CRIPTO were identified as a diagnostic and prognostic marker, whereas CRIPTO expression in tumor tissues was associated with worse prognosis." (PMID 35719935, 2022). "miR-15b and miR-205 have been inversely correlated with CRIPTO expression in gliomas and non-small cell lung cancer (NSCLC) respectively." (PMID 34576327, 2021).
prostate carcinoma (5 papers, 2015 to 2025). A carcinoma that arises from epithelial cells of the prostate gland. "In summary, the loss of CRIPTO influenced the progress of advanced prostate cancer stages, leading to a decrease in invasive carcinoma and changes in stromal composition." (PMID 39592836, 2025). "Beyond prostate cancer (PCa), CRIPTO has been implicated in colon, lung, breast, liver (hepatocellular carcinoma), and brain (glioblastoma)." (PMID 39592836, 2025). "To explore the expression pattern of CRIPTO in PCa, we analyzed CRIPTO protein expression on a tissue microarray (TMA) consisting of primary prostate cancer tissues from the European Multicenter High-Risk Prostate Cancer Clinical and Translational research group (EMPaCT)." (PMID 39592836, 2025). "Our approach involved gaining insight into the role of CRIPTO signaling in castration-resistant Nkx3.1-expressing cells (CARNs), targets for oncogenic transformation in prostate cancer (PCa), by integrating the existing Criptoflox/flox into CARNs model." (PMID 39592836, 2025). "In a prospective study of 138 patients with prostate cancer, low CRIPTO expression following radical prostatectomy predicted biochemical-recurrence-free survival." (PMID 34576327, 2021). "CRIPTO (Teratocarcinoma-derived growth factor 1), one of the major regulators, participate in the development of prostate cancer." (PMID 32850882, 2020). "Here, we find CRIPTO expression as especially high in a subgroup of primary prostate carcinomas with poorer outcome, wherein resides cancer cell clones with mesenchymal traits." (PMID 25596738, 2015). "Knockdown of CRIPTO in a prostate cancer murine model also severely attenuated tumor growth." (PMID 34576327, 2021). "Experimental studies in PCa models showed that one notable function of CRIPTO expression in prostate carcinoma cells may be to augment PI3K/AKT and FGFR1 signaling, which promotes epithelial-mesenchymal transition and sustains a mesenchymal state." (PMID 25596738, 2015). "Similarly, in prostate cancer high CRIPTO expression correlates with poor outcomes." (PMID 34576327, 2021). "Consistent with the known upregulation of MYC in human prostate cancer, the IHC staining quantification showed robust MYC expression which correlated with CRIPTO expression (**p = 0.0098)." (PMID 39592836, 2025). "This was particularly intriguing as it was associated with PSA progression, further suggesting a potential synergistic role between CRIPTO, MYC targets, and the advancement of prostate cancer-promoting tumorigenesis." (PMID 39592836, 2025). "CRIPTO has also been proposed to regulate EMT and stemness via stabilizing the WNT pathway regulator disheveled segment polarity protein 3 (DVL3) in several tumor types including prostate cancer and hepatocellular carcinoma." (PMID 34576327, 2021). "CRIPTO-antagonistic actions of select BMP proteins may further substantiate this point, for instance following breast cancer colonization in the lung after intravasation following metastasis, or metastasis to the bone from breast and prostate cancer models in vivo." (PMID 34576327, 2021).
embryonal carcinoma (4 papers, 2013 to 2025). A non-seminomatous malignant germ cell tumor characterized by the presence of large germ cells with abundant cytoplasm resembling epithelial cells, geographic necrosis, high mitotic activity, and pseudoglandular and pseudopapillary structures formation. "For instance, the embryonal carcinoma cell line NTERA2 contains both CRIPTO-high and CRIPTO-low cells, which are associated with high and low tumorigenic capacities respectively." (PMID 34576327, 2021). "Conversely, CRIPTO is directly repressed by the orphan nuclear receptor germ cell nuclear factor (GCNF) which binds to the promoter during retinoic acid-induced differentiation of human embryonic carcinoma cells and by the miR-15a/16 cluster which bind to the 3’UTR of CRIPTO mRNA." (PMID 25629528, 2015).
glioblastoma (4 papers, 2015 to 2025). The most malignant astrocytic tumor (WHO grade IV). "Alowaidi and colleagues showed using KEGG pathways database that 47 signaling pathways presented significant changes in protein phosphorylation following CRIPTO stimulation in glioblastoma (GBM) cells." (PMID 34576327, 2021).
colon carcinoma (3 papers, 2015 to 2022). "Like CRIPTO, TNS-1 and GAS-7, the other two genes in the associated regions present in the network, are both involved in breast and colon cancer." (PMID 25629528, 2015). "The fact that hepatocyte-derived ECM from the liver, which is a common metastatic site for colon cancer, stimulates CRIPTO expression in highly metastatic colon cancer cell line KM12SM may indicate a selective advantage for CRIPTO-expressing colon cancer cells to metastasize to the liver." (PMID 34576327, 2021). "In light of the recent implication of CRIPTO in fibrosis it is interesting to consider how different ECM substrates (these could include e.g., specific signaling domains and varying stiffness) may lead to different levels of CRIPTO expression induction in colon cancer cells." (PMID 34576327, 2021).
hepatocellular carcinoma (3 papers, 2019 to 2021). A malignant tumor that arises from hepatocytes. "For instance, high CRIPTO levels have been reported in hepatocellular carcinoma (HCC) tissue but also in patients with hepatitis B-induced HCC." (PMID 34576327, 2021). "Oncofetal protein, CRIPTO, is silenced during homeostatic postnatal life and often re-expressed in different neoplastic processes, such as hepatocellular carcinoma." (PMID 34943832, 2021). "CRIPTO has been identified as a marker of CSCs in several cancer models including prostate, melanoma, colon, esophageal and hepatocellular carcinoma (HCC)." (PMID 34576327, 2021). "However, CRIPTO levels are upregulated in an impressive variety of cancers including prostate, hepatocellular carcinoma, pancreatic, bladder, colon, breast, lung, and gastric cancer." (PMID 34576327, 2021). "In contrast to SPARC, GRP78, which is often upregulated on the cell surface in malignancy, can interact with PI3K, CRIPTO, IGF1-R in the breast, prostate, and hepatoma cells, respectively, to promote oncogenic events." (PMID 31243264, 2019).
prostate tumor (3 papers, 2015 to 2021). "CRIPTO expression is predominantly restricted to a stem-like subpopulation of prostate tumor cells and CRIPTO-knockdown reduces the metastatic capacity of these cells, suggesting that CRIPTO plays a role in tumor progression." (PMID 34576327, 2021). "Moreover, in aggressive prostate tumours, a novel molecular network, involving CRIPTO, AKT and FGFR signalling, was described in mesenchymal-like cancer cells." (PMID 27711186, 2016). "Collectively, these findings suggest a novel molecular network, involving CRIPTO, AKT, and FGFR signaling, in favor of the emergence of mesenchymal-like cancer cells during the development of aggressive prostate tumors." (PMID 25596738, 2015).
teratocarcinoma (3 papers, 2015 to 2022). A germ cell tumor characterized by the presence of an embryonal carcinoma component and a teratoma component. "To explore the possibility that this SNP, located in the 5’UTR of CRIPTO gene, might influence CRIPTO transcription we tested the SNP allele effect on the transcriptional activity in the NTERA2 teratocarcinoma cell line, expressing high levels of CRIPTO." (PMID 25629528, 2015). "In the present study, we aimed to investigate the presence of CRIPTO in teratocarcinoma EVs as well as its functional significance." (PMID 35954365, 2022). "Teratocarcinoma EVs contain the oncofetal protein CRIPTO, that is involved in the observed reduction of GBM cell migration." (PMID 35954365, 2022). "Our analysis showing CRIPTO also in sEVs and lEVs derived from teratocarcinoma cells, coupled with the previous finding of Hu and coauthors (2021), led us to hypothesize a more general mechanism that could involve many types of cancer." (PMID 35954365, 2022).
breast carcinoma (2 papers, 2020 to 2021). "Our (BTS) recent work suggests that CRIPTO localizes along hypoxic, acellular domains in a murine breast cancer xenograft model." (PMID 34576327, 2021). "Consistent with this, in cancer, we have shown inhibition of CRIPTO with a soluble inhibitor, Alk4L75A-Fc, reduces primary and metastatic tumor burden in a breast cancer xenograft model." (PMID 34576327, 2021). "PR expression also contributes to major molecular phenotype descriptions in breast cancer, though the potential subtype specific effects of CRIPTO blockade as a breast cancer therapy are underexplored." (PMID 34576327, 2021). "Supporting the importance of contextual alterations to the surface proteome, GRP78 and CRIPTO co-localize along acellular regions within xenograft mammary tumors." (PMID 34576327, 2021). "Conversely, CRIPTO knockdown or knockout reduces the migratory and invasive properties of cells derived from prostatic, liver, renal and mammary tumor tissues, suggesting it has broad tissue type-independent functions that support tumorigenesis." (PMID 34576327, 2021). "Together, these results are consistent with CRIPTO/GRP78 signaling being stress responsive in breast cancer cells." (PMID 33187540, 2020). "Similarly, in vivo experiments showed that overexpression of CRIPTO in MCF-7 breast cancer cell xenografts enhanced tumor neovascularization." (PMID 34576327, 2021). "These signaling activities require CRIPTO binding to cell surface glucose regulated protein 78 kDa (GRP78), an endoplasmic reticulum chaperone that localizes to the cell surface under stress conditions and which, like CRIPTO, is overexpressed in breast cancers." (PMID 33187540, 2020). "Results presented here indicate that targeting CRIPTO with ALK4L75A-Fc may have potential as such a therapy since it inhibits breast cancer cell adaptation to microenvironmental challenges and associated stem-like and EMT phenotypes." (PMID 33187540, 2020). "However, CRIPTO signaling blockade in MDA-MB-231 mammary tumor xenografts attenuates primary tumor burden, although inhibition of CRIPTO is not sufficient to cause regression." (PMID 34576327, 2021). "We previously developed a CRIPTO antagonist, ALK4L75A-Fc, and showed that it causes loss of the stem cell phenotype in normal mammary epithelia suggesting it may similarly inhibit CRIPTO-dependent plasticity in breast cancer cells." (PMID 33187540, 2020). "CRIPTO’s effects on breast cancer cells are likely mediated by its joint modulation of the TGF-β pathway and growth factor-like signaling (i.e., activation of SRC/MAPK/PI3K pathways), and there may also be important roles for other pathways regulated by CRIPTO including WNT and NOTCH." (PMID 33187540, 2020). "However, we note that CRIPTO is overexpressed in a range of cancers including over 80% of breast cancers, and accordingly, some preliminary studies have indicated CRIPTO effects in both ER+ and Her2+ breast cancers." (PMID 33187540, 2020). "CRIPTO promotes anchorage-independent growth, migration, invasion, and EMT in mammary epithelial cells and breast cancer cell lines in vitro." (PMID 33187540, 2020). "In addition, CRIPTO knockdown inhibits proliferation of human MDA-MB-468 and SKBR3 breast cancer cell lines in vitro, while CRIPTO knockdown in a triple negative breast cancer (TNBC)-like transplantable mouse mammary tumor model blocks progression." (PMID 33187540, 2020).
colorectal cancer (2 papers, 2021 to 2022). A primary or metastatic malignant neoplasm that affects the colon or rectum. "In colorectal cancer (CRC) CRIPTO levels affected the size of the CSCs compartment, as CRIPTO downregulation was able to inhibit CSCs survival, tumor growth and metastasis formation." (PMID 35719935, 2022). "Capitalizing on these findings, CRIPTO is now offered as a part of a point of care screening panel for colorectal cancer including CEA, and an undisclosed extracellular matrix protein." (PMID 34576327, 2021).
germ cell tumor (2 papers, 2020 to 2021). A benign or malignant, gonadal or extragonadal neoplasm that originates from germ cells. "Even in broadly “stem-like” germ cell tumors there is heterogeneity of CRIPTO expression." (PMID 34576327, 2021). "Functionally important levels of CRIPTO in non-germ cells cancers appear to be orders of magnitude lower than seen in germ cell tumors such as NTERA and NCCIT." (PMID 34576327, 2021).
glioma (2 papers, 2021 to 2024). A benign or malignant brain and spinal cord tumor that arises from glial cells (astrocytes, oligodendrocytes, ependymal cells). "However, only miR-15b has been shown to reduce CRIPTO expression and subsequently reduce proliferation in glioma cell lines." (PMID 34576327, 2021). "Similarly, in a glioma cell line, exogenous CRIPTO upregulates endogenous CRIPTO expression in a sub-population of cells." (PMID 34576327, 2021).
liver cirrhosis (2 papers, 2019 to 2021). "The mean CRIPTO level was significantly (p = 0.03) higher in the end-stage liver cirrhosis group compared to that of the healthy controls." (PMID 34943832, 2021). "CRIPTO expression was evaluated in liver cirrhosis specimens and in circulating blood levels of patients with cirrhosis prior to and after removal of the fibrogenic liver by LT." (PMID 34943832, 2021).
myocardial infarction (2 papers, 2021). Gross necrosis of the myocardium, as a result of interruption of the blood supply to the area, as in coronary thrombosis. "Murine heart tissues were evaluated for CRIPTO and fibrotic markers in three models of heart injury following myocardial infarction, pressure overload, and ex vivo induced fibrosis." (PMID 34943832, 2021). "In three models of heart injury following myocardial infarction, pressure overload, and ex vivo induced fibrosis, CRIPTO was found to be temporally upregulated." (PMID 34943832, 2021). "During myocardial infarction CRIPTO is upregulated initially in cardiac interstitial cells, followed by expression in αSMA-positive myofibroblasts throughout the infarct area." (PMID 34943832, 2021).
perihilar cholangiocarcinoma (2 papers, 2022). "In particular, very recently CRIPTO has been found on the surface on sEVs released by another type of cancer cell: the perihilar cholangiocarcinoma (PHCCA) cells." (PMID 35954365, 2022). "Very recently, Hu and coauthors reported also the presence of CRIPTO on the membrane of the sEVs released by perihilar cholangiocarcinoma (PHCCA) cells." (PMID 35954365, 2022).
seminoma (2 papers, 2020 to 2022). A radiosensitive malignant germ cell tumor found in the testis (especially undescended), and extragonadal sites (anterior mediastinum and pineal gland). "Significantly higher CRIPTO concentration was found in sera of non-seminomas compared to controls (p = 0.0297), and in stage II/III disease compared to stage I (p = 0.0052, p = 0.0097)." (PMID 32210110, 2020).
alcoholic liver diseases (1 paper, 2021). A disorder caused by damage to the liver parenchyma due to alcohol consumption. "CRIPTO levels are also higher in liver tissue samples of patients suffering from alcoholic liver disease (ALD) or viral- induced liver cirrhosis compared to control group, while CRIPTO levels in plasma decrease after liver transplantation (LT) in paired pre- and post-LT samples." (PMID 34576327, 2021).